CDCA3 (cell division cycle associated 3)
Diseases named in the same sentence as CDCA3 in open-access papers (continued):
Sharing a sentence is not in itself a finding about the gene and the disease.
breast invasive carcinoma (2 papers, 2018 to 2020). "By comparison with the top 200 up-regulated genes in breast invasive carcinoma (BRCA) from GEPIA database, only three genes (KIF23, PRC1, CDCA3) were screened for further research." (PMID 32944002, 2020).
cutaneous melanoma (2 papers, 2021 to 2022). A primary melanoma arising from atypical melanocytes in the skin. "The underlying processes of CDCA3 in cutaneous melanoma should be clarified in further investigations." (PMID 36713580, 2022). "Finally, we revealed that knockdown of cell division cycle-associated gene 3 (CDCA3) significantly suppressed the proliferation and migration ability of cutaneous melanoma cells." (PMID 36713580, 2022). "As anticipated, we discovered that knocking down CDCA3 decreased the malignant phenotype of cutaneous melanoma cells, verifying that CDCA3 expression is a promising target for cutaneous melanoma treatment." (PMID 36713580, 2022). "The findings indicated that suppression of CDCA3 in cutaneous melanoma cells noticeably reduces the expression of C-Myc and CyclinD1." (PMID 36713580, 2022). "A pancancer analysis of CDCA3 was performed, showing that cutaneous melanoma experienced one of the most remarkably increases in CDCA3 expression among all cancer types." (PMID 36713580, 2022). "To gain insight into how CDCA3 affects the course of cutaneous melanoma, we inhibited the expression of CDCA3 in cutaneous melanoma cells by transfecting them with si-CDCA3." (PMID 36713580, 2022). "The effects of CDCA3 on cutaneous melanoma cell proliferation and migration were subsequently evaluated." (PMID 36713580, 2022). "The three CCP-related gene signatures–HSD11B1, NDRG1 and CDCA3–may each independently predict the clinical outcomes of cutaneous melanoma patients, according to our prognostic study (both in OS and DSS)." (PMID 36713580, 2022). "We compared 236 cutaneous melanoma CDCA3-high samples with 236 CDCA3-low samples." (PMID 36713580, 2022). "Moreover, we knocked down the expression of CDCA3 in vitro to detect the impact on the proliferation and migration of cutaneous melanoma cells." (PMID 36713580, 2022). "Collectively, CDCA3 promotes the viability of cutaneous melanoma cells." (PMID 36713580, 2022). "In addition, we determined the relative expression levels of C-Myc and CyclinD1 because we hypothesized that CDCA3 is involved in the control of cell cycle-related proteins to carry out its biological role in cutaneous melanoma." (PMID 36713580, 2022). "However, the effect of CDCA3 on prognosis in cutaneous melanoma remains unclear." (PMID 36713580, 2022).
dengue fever (2 papers, 2022 to 2024). "IFI27, TPX2, CDT1 and CDCA3 are particularly known for their role in cancer, and TPX2 also for its role in the context of infectious diseases, in particular dengue fever." (PMID 35220956, 2022).
esophageal carcinoma (2 papers, 2021). A primary or metastatic malignant neoplasm involving the esophagus. "Studies have shown that the expression levels of CDCA3 and CENPF are correlated in esophageal carcinoma." (PMID 34905505, 2021).
liver cirrhosis (2 papers, 2024 to 2025). "In HCC, a four-gene combination involving KIF4A, UBE2T, CDCA3, and CDCA5 can track disease progression from chronic active hepatitis B (CAH-B) and liver cirrhosis (LC) to HCC." (PMID 41361459, 2025). "However, no study reported the role of CDCA3 in chronic active hepatitis B and liver cirrhosis." (PMID 38890649, 2024).
prostate adenocarcinoma (2 papers, 2021 to 2023). "The results showed that CDCA3 was highly expressed in prostate adenocarcinoma, and other cancer types compared with each normal tissue." (PMID 37682152, 2023).
triple-negative breast carcinoma (2 papers, 2020 to 2021). An invasive breast carcinoma which is negative for expression of estrogen receptor (ER), progesterone receptor (PR), and human epidermal growth factor receptor 2 (HER2). "CircUBE2D2 enhanced cell proliferation and doxorubicin resistance in triple-negative breast cancer cells by controlling miR-512-3p/cell division cycle associated protein-3 (CDCA3) axis." (PMID 34537072, 2021).
breast tumors (1 paper, 2020). "In addition, 6/7 PC-CIN genes (CEP55, UBE2C, MELK, TPX2, PTTG1, and CDCA3) were also found to be among the top DEGs identified through comparison of high aneuploidy versus low aneuploidy breast tumors in TCGA." (PMID 32380981, 2020).
endometrial carcinoma (1 paper, 2020). A malignant tumor arising from the epithelium that lines the cavity of the uterine body. "When it comes to uterine mixed endometrial carcinoma, another distinctive pattern emerged and the most were the high mRNA expression of almost all CDCA members except CDCA3/7, and the missense mutation of NUF2, CDCA2/3/5, CBX2, CDCA7/8." (PMID 32913454, 2020).
glioblastoma (1 paper, 2024). The most malignant astrocytic tumor (WHO grade IV). "To further assess the prognostic significance of CDCA3 in glioblastoma (GBM) and LGG, we conducted comprehensive analyses using data from the TCGA, CGGA, and Rembrandt datasets." (PMID 38728485, 2024).
heart failure (1 paper, 2024). Inability of the heart to pump blood at an adequate rate to meet tissue metabolic requirements. "Although it is upregulated in heart failure, the role of CDCA3 in cardiovascular disease remains unknown." (PMID 38994368, 2024).
invasive ductal breast carcinoma (1 paper, 2018). The most common type of invasive breast carcinoma, accounting for approximately 70% of breast carcinomas. "According to the previous studies, the overexpression of CDCA3 in invasive ductal breast carcinoma was likely to associate with oral carcinogenesis by decreasing the levels of cyclin-dependent kinase inhibitors, which resulted in cell cycle arrest at G1." (PMID 29467944, 2018). "Our data revealed similar CDCA3 expression patterns to previous studies using whole transcription profiles of invasive ductal breast carcinoma obtained by either microarrays or RNA-sequence data." (PMID 29467944, 2018).
nasopharyngitis (1 paper, 2022). An inflammatory process that affects the nasopharynx. "CDCA genes were broadly upregulated in NPC tissues compared to nasopharyngitis tissues, and high expression of CDCA3/5/8 indicated worse prognosis in NPC." (PMID 35237510, 2022).
neuroblastoma (1 paper, 2025). Neuroblastoma (NB) is the most common solid, extracranial childhood tumor. "Examination of ChIP-seq data from neuroblastoma cells (GSE13829553) identifies a significant MYC binding peak within the CDCA3 promoter region, further supported by JASPAR database predictions of a potential E-box sequence in this region." (PMID 39980052, 2025).
serous ovarian cancer (1 paper, 2021). "By analysis of the clinical data, we found that CDCA3 and UBE2C were associated with poor prognosis in serous ovarian cancer patients." (PMID 34577856, 2021). "We suggested that CDCA3 and UBE2C may represent valuable biomarkers to predict the outcome of serous ovarian cancer." (PMID 34577856, 2021). "This showed that higher expressions of CDCA3, CENPF, NCAPG, RRM2, UBE2C, and NBEA were associated with worse OS regardless of serous ovarian cancer stages." (PMID 34577856, 2021).
soft tissue sarcoma (1 paper, 2019). A malignant neoplasm arising from muscle tissue, adipose tissue, blood vessels, fibrous tissue, or other supportive tissues excluding the bones. "Interestingly we found only one gene, CDCA3, overlapped between the prognostic genes we identified in the TCGA soft tissue sarcoma data and the CINSARC prognosticator." (PMID 30785874, 2019). "Furthermore, only one gene (CDCA3 identified in STLMS) was found to overlap between the 67 described CINSARC genes and the soft tissue sarcoma subtype specific prognostic genes identified in the current study." (PMID 30785874, 2019).
uterine endometrioid carcinoma (1 paper, 2020). "In uterine endometrioid carcinoma, the prevalent high mRNA expression of almost all CDCAs except CDCA7, the amplification of NUF2, CDCA3/5, the deep deletion of CDCA2 and the missense mutation of CDCA7 presented the most common altered genetic events." (PMID 32913454, 2020).
tumor (54 papers, 2012 to 2025). "Often overexpressed in tumor tissues, CDCA3 is linked to carcinogenic qualities in a number of malignancies, such as gastric, non-small-cell lung, prostate, and colorectal." (PMID 40963614, 2025). "CDCA3 is frequently upregulated in the tumor tissues and is associated with oncogenic properties in several cancers, including HCC." (PMID 38890649, 2024). "Our findings point to the possibility of exploiting levels of cell division cycle associated protein-3 (CDCA3) to improve response of NSCLC tumours to therapy." (PMID 34050247, 2021). "Recently, some studies have suggested that CDCA3 is expressed differently between normal tissues and tumor tissues; however, only few studies have explained the underlying mechanism and pathways of CDCA3 expression in HCC." (PMID 33604380, 2021). "The results showed that high expression of CDCA3 was associated with poor prognosis of patients, high levels of infiltrating immune cells, and tumor purity in HCC and ACC." (PMID 33604380, 2021). "Given the association in NSCLC tumours, we next examined CDCA3 expression in a small panel of LUAD cell lines." (PMID 34572879, 2021). "CDCA3 expression was associated with the levels of immune cell infiltration and was positively correlated with tumor purity." (PMID 33604380, 2021). "The RFS of patients with a medium expression level of CDCA3 showed an association to all tumor subtypes." (PMID 29467944, 2018). "The current study shows the results of a comprehensive analysis of aberrant expression of CDCA3 in OSCCs that are clinically and functionally linked to tumor progression." (PMID 22839099, 2012). "Therefore, CDCA3 expression was associated with tumor-infiltrating immune cells and caused poor outcomes depending on the type of tumor-infiltrating immune cells in HCC." (PMID 33604380, 2021). "CDCA3 plays an important role in the carcinogenesis of various cancers; however, the association between CDCA3 expression, prognosis of patients, and immune infiltration in the tumor microenvironment is still unknown." (PMID 33604380, 2021). "Notably, the expression of CDCA3 was also associated with tumor purity (partial cor = 0.153, p = 4.33E − 03), and it showed that the CDCA3 expression had a positive correlation with tumor purity in HCC." (PMID 33604380, 2021). "Functional studies revealed that inhibition of miR-134-5p or overexpression of CDCA3 reversed the suppressive effects of curcumin on tumor cell growth and invasion, highlighting the regulatory axis." (PMID 40969596, 2025). "In vivo experiments supported these findings, as curcumin treatment significantly reduced tumor growth in mice, accompanied by increased miR-134-5p expression and reduced CDCA3 and CDK1 levels." (PMID 40969596, 2025). "Further exploration of CDCA2 and CDCA3 effects on the tumor microenvironment and metastasis is essential to develop balanced strategies for effective cancer treatment." (PMID 39924497, 2025). "It was considered to be a prognostic factor of RCC, and the upregulation of CDCA3 was associated with advanced TNM stage, tumor grade and immune cell infiltration." (PMID 37064095, 2023). "Our results showed that CDCA3 affected tumor infiltration of various immune cells, including CD8+ T cells in endogenous and exogenous data." (PMID 36213833, 2022). "Scholars revealed that CDCA3 influence many tumor progression and treatment through a variety of pathways and is associated with poorer prognosis." (PMID 36213833, 2022). "This directly proved that the functional localization of CDCA3 was a key regulatory protein in the cell cycle, and its abnormal expression can affect tumor progression and prognosis." (PMID 36213833, 2022). "In summary, CDCA3 can be an independent prognostic factor and reflect the rate of tumor progression tumor progression in RCC." (PMID 36213833, 2022). "Our study suggested that CDCA3 can independently predict prognosis and affect tumor progression in RCC." (PMID 36213833, 2022).
tumor (continued). "We also explored the relationship between CDCA3 expression and tumor-infiltrating immune cells using the Tumor Immune Estimation Resource (TIMER) database." (PMID 33604380, 2021). "Compared with the corresponding normal tissues, the expression of CDCA3 was upregulated in tumor tissues of various human cancers including HCC." (PMID 33604380, 2021). "We observed higher CDCA3 expression in tumor tissues than in corresponding normal tissues, and higher CDCA3 expression resulted in poorer outcomes in patients with HCC." (PMID 33604380, 2021). "In the current study, our findings point to the possibility of exploiting expression of CDCA3 as a strategy to identify TKI responsive EGFR mutant tumours." (PMID 34572879, 2021). "Collectively, these results suggest that CDCA3 expression correlates with DNA-based and functional measures of genome instability where CDCA3high tumours are more sensitive to platinum agents." (PMID 34050247, 2021). "We verified our results using TIMER, and our results were validated as CDCA3 expression was different between tumor and normal tissue samples." (PMID 33604380, 2021). "In the present study, we examined the potential of CDCA3 as a biomarker for tumour cell response to platinum-based chemotherapy." (PMID 34050247, 2021). "Collectively, these results provide evidence that CDCA3 is involved in immune escape and immunosuppression in the tumor microenvironment." (PMID 33604380, 2021). "We demonstrate that in patients and in vitro analyses, CDCA3 levels correlate with measures of genome instability and platinum sensitivity, whereby CDCA3high tumours are sensitive to cisplatin and carboplatin." (PMID 34050247, 2021). "hsa-miR-145-5p, low-expressed in CC, targets CDCA3 to play a tumor suppressor role, acting as a biomarker for diagnosis and treatment." (PMID 34337040, 2021). "Immune cell infiltration is gaining increasing attention in tumor biology research, however, relatively few studies have explored the relationship between CDCA3 and immune cell infiltration." (PMID 34905505, 2021). "CDCA3 was highly expressed in the tumor tissues than in the adjacent normal tissues in various cancers, including HCC." (PMID 33604380, 2021). "We also identified that CDCA3 is functionally important in mediating proficient G2/M cell cycle progression and tumour cell proliferation where depletion of this protein induces tumour cell senescence." (PMID 34050247, 2021). "Regarding PAAD, increased CDCA expression along with advanced PAAD tumor stage, NUF2, CDCA2, CDCA3, CDCA4 and CDCA5 expression are risk factors for poor prognosis, while CBX2 expression is a protective factor (P < 0.05)." (PMID 33437202, 2021). "Chi square test for GSE13507 dataset further showed that the expression level of CDCA3 was not only related to clinical grade but also related to muscularis invasion, lymph node metastasis and tumor progression." (PMID 33980246, 2021). "We analyzed CDCA3 expression in normal samples from the GTEx database and the TCGA and 33 tumor samples in TCGA." (PMID 34905505, 2021). "More recently, we have identified that elevated levels of CDCA3 also correlate with response to platinum-based chemotherapy, whereby CDCA3high tumours exhibit greater sensitivity to therapy." (PMID 34572879, 2021). "Researches have confirmed the uncontrolled elevation of CDCA3 exerted a specific effect on tumor progression." (PMID 33980246, 2021). "Consistently, CDCA3 expression was significantly elevated in tumours exhibiting at least one whole-genome duplication in ADC and SqCC." (PMID 34050247, 2021). "The results showed that expression of CDCA3 was significantly correlated with the tumor grade (p = 1.069E − 09) and stage (p = 3.9E − 04)." (PMID 33604380, 2021). "While CX-4945 enhances chemotherapy in other solid malignancies, our findings indicate that in NSCLC, a strategy to first select tumours based on CDCA3 expression would enhance CX-4945 potency and sensitivity to platinum agents." (PMID 34050247, 2021).